NLRP3 (NLR family pyrin domain containing 3)
Diseases named in the same sentence as NLRP3 in open-access papers (continued):
Sharing a sentence is not in itself a finding about the gene and the disease.
Sepsis (continued). "In a mouse sepsis model, GYY4137 treatment reduced NLRP3 and caspase-1, and alleviated lung injury." (PMID 36139861, 2022). "Taken together, HG exerts a protective effect against sepsis-induced ALI by reducing the inflammatory response and macrophage M1 polarization, which may involve NF-κB pathway-modulated NLRP3 inflammasome activation." (PMID 35266443, 2022). "Taken together, these results suggest that PHZ-OH protects against organ dysfunction and lethality in sepsis independent of NLRP3 inflammasome." (PMID 35982051, 2022). "The western blot showed that CLP-induced sepsis promoted GSDMD, caspase-1, and NLRP3 expression." (PMID 35979014, 2022). "In sepsis, whether HSF1 can participate in the activation of the NLRP3 inflammasome by regulating the expression of TRAF3 is still unclear." (PMID 35720321, 2022). "According to previous studies, we hypothesized that up-regulation of MIF in sepsis-induced AKI makes a renal damage effect and promotes NLRP3 inflammasome activation to aggravate cell pyroptosis." (PMID 35165294, 2022). "Consistently, PHZ-OH, a novel 1-hydroxy phenothiazinium-based small molecule identified in this study, significantly prevents coagulation, organ dysfunction and death in sepsis by inhibiting caspase-11 signaling rather than NLRP3 inflammasome." (PMID 35982051, 2022). "Based on above findings, we hypothesized that HG might play a role in sepsis-induced ALI by regulating inflammatory response and macrophage activation through the NLRP3/NF-κB axis." (PMID 35266443, 2022). "Moreover, levels of HMBOX1 in heart tissues were dramatically decreased, while expression of pyroptosis-related proteins NLRP3, caspase-1, and GSDMD-N were all upregulated after treatment of sepsis-exos." (PMID 35345489, 2022). "Surprisingly, several drugs targeting the downstream of NLRP3 have conducted clinical trials for certain diseases, and to our knowledge, these drugs have not been investigated for the treatment of sepsis-related skeletal muscle atrophy yet." (PMID 36405697, 2022). "The elevated secretion of IL-1β and IL-18, and expression pattern of HMBOX1, NF-κB (cytoplasm), nuclear NF-κB, NLRP3, caspase-1, and GSDMD-N were all reversed by overexpression of HMBOX1, showing that sepsis-exos and miR-885-5p mimic had similar effects on AC16 cells." (PMID 35345489, 2022). "It has been reported that inactivation of NLRP3 inflammasomes and inhibition of caspase-1-mediated cleavage of GSDMD could prevent pyroptosis in LPS-induced sepsis in a mouse model, thereby alleviating the septic shock." (PMID 35508474, 2022). "In the current study, activation of the NLRP3 inflammasome accompanied by increased secretion of IL-1β, IL-18, and HMGB1 was noted in CD11c+CD11bintMHC-IIhiCD115−Flt3+ splenic DCs after induction of sepsis." (PMID 34741186, 2021). "S100A12, a pro-inflammatory factor, can promote inflammation and cell apoptosis in ARDS induced by sepsis through activating the NLRP3 inflammasome signaling pathway, which is a potential biomarker of pulmonary injuries in the clinical diagnosis of ARDS induced by sepsis." (PMID 34393665, 2021). "The underlying mechanism is that dexmetomidine may up-regulate the expression of Cav-1 down-regulated by sepsis, which may conduce to the suppression of TLR-4/NLRP3-mediated signaling pathway, at least in part." (PMID 33558888, 2021). "We can almost conclude that NLRP3 activation does not have a positive effect on neutrophil recruitment and bacterial clearance during sepsis." (PMID 34257519, 2021). "As a result, Nlrp3 KO mice show a normal cardiac function in sepsis without cardiac atrophy and preserved expression of pro‐inflammatory cytokines." (PMID 34472725, 2021). "Upregulation of LBH could significantly reduce the NLRP3 and ASC protein expression in lung tissues of sepsis-induced ALI mouse model (P < 0.001)." (PMID 33553423, 2021).
Sepsis (continued). "In sum, the activation of TLR2, TLR4, TLR7, TLR9 and NLRP3 are almost certainly maintained by DAMPs in severe COVID-19, ALI/ARDS and sepsis and may need to be therapeutically addressed." (PMID 33672738, 2021). "The data presented here reveal a protective role of cystatin C in LPS-induced sepsis and NLRP3 inflammasome activation that is independent of protease inhibition." (PMID 34440840, 2021). "Research has indicated that by affecting NLRP3 inflammasome, autophagy participates in many diseases, including inflammatory lung disease, sepsis, nephropathy, gouty arthritis, inflammatory bowel disease, familial Mediterranean fever (FMF), and sepsis." (PMID 34884572, 2021). "Similarly, we found that significant activation of NLRP3–ASC–CASP-1-mediated pyroptosis and excessive release of inflammatory cytokines are mainly characteristics of the initial hyperinflammatory phase of sepsis." (PMID 34741186, 2021). "Although our data suggest that the NLRP3 pathway primarily activates IL‐1β in sepsis, further studies are needed to elucidate the role of the non‐canonical and alternative IL‐1β‐activating pathway in sepsis." (PMID 34472725, 2021). "In Nlrp3 knockout mice, sepsis can no longer activate the NLRP3 inflammasome, generation of IL‐1ß is much reduced, and activation of NF‐κB as well as NF‐κB signalling is attenuated, which maintains cardiomyocyte size, deformability, contraction and relaxation." (PMID 34472725, 2021). "In summary, these data indicate that deletion of Nlrp3 is accompanied by less pronounced changes in overall gene expression, a reduced immune response, a reduction in NF‐κB signalling and increased ALP in the heart during sepsis." (PMID 34472725, 2021). "LBH overexpression could markedly downregulate the expression of NLRP3 and ASC in lung tissues of sepsis-induced ALI mouse model (P < 0.001)." (PMID 33553423, 2021). "Inhibiting the negative effects of ROS and NLRP3 inflammasomes therefore provides the possibility of reversing the excessive inflammation during sepsis." (PMID 33324236, 2020). "Although sufficient evidence has demonstrated negative effects of the ROS/NLRP3 inflammasome pathway during sepsis, some studies have also suggested an anti-inflammatory effect of ROS." (PMID 33324236, 2020). "And it was found that estrogen administration could dramatically reverse sepsis-induced up-regulation of cleaved GSDMD and caspase-1 as well as NLRP3." (PMID 33002070, 2020). "Based on our previous findings and those of other studies, in the present study, we hypothesized that Parkin-mediated mitophagy plays a role in the protective effects of PD against MD and NLRP3 activation in SI-AKI and established a mouse model of sepsis." (PMID 32131850, 2020). "The increase in surface expression of P2X7 receptors in monocytes during sepsis was similar in both NLRP3 compromised and non-compromised septic patients." (PMID 31221993, 2019). "Normal release of IL-1β and ASC-speck formation was found in non-compromised NLRP3 septic patients during the course of the first 5 days of sepsis." (PMID 31221993, 2019). "Our results show that ATP-induced NLRP3 inflammasome does not activate correctly in the blood leukocytes of sepsis patients." (PMID 31221993, 2019). "In summary, our data suggest the NLRP3/caspase-1 signaling pathway may play a vital role in neuronal pyroptosis and cognitive impairments in the development of SAE secondary to a sepsis." (PMID 30276509, 2019). "In contrast, Nlrp3 KO did not lose body or liver weight, while spleen weight increased in these mice during sepsis." (PMID 28097512, 2017). "The present study demonstrates that GIK protects intestinal mucosal barrier function in CLP-induced sepsis and that UCP2 and the NLRP3/caspase-1/IL-1β signaling pathway may be involved in this process." (PMID 28428961, 2017). "The histological pictures show that myofibers of WT but not of Nlrp3 KO CLP atrophied during sepsis." (PMID 28097512, 2017).
Sepsis (continued). "Given the role of the NLRP3 inflammasome in sepsis-induced AKI, we investigated whether SIRT3 knockout had an effect on AKI-related inflammatory responses by assessing NLRP3 levels and function in response to CLP." (PMID 27620507, 2016). "Our study provided evidence that CORM-2 treatment protected against sepsis-induced AKI and inhibited NLRP3 inflammasome activation, and suggested that CORM-2 could be a potential therapeutic candidate for treating sepsis-induced AKI." (PMID 26334271, 2015). "Therefore, the aim of the present study was to investigate the effects of CORM-2 on sepsis-induced AKI and NLRP3 inflammasome activation in rats." (PMID 26334271, 2015). "In sepsis-induced acute kidney injury, exogenous Zn2+ binds to SIRT1 and significantly inhibits its activity, which in turn upregulates Parkin acetylation to promote mitochondrial autophagy and suppress the activation of the NLRP3 inflammasome and cell pyroptosis." (PMID 41513612, 2026). "Furthermore, SIRT1 deficiency promotes excessive mtROS generation and mtDNA leakage into the cytoplasm by impairing late endosome-mediated mitochondrial autophagy, leading to enhanced activation of NLRP3 and STING, which results in pulmonary endothelial dysfunction in sepsis." (PMID 40766066, 2025). "Combining NLRP3/GSDMD inhibitors with NET/MET modulators may reduce inflammation, microthrombosis, and multiorgan failure in sepsis and COVID-19, provided it is applied within the optimal therapeutic window, guided by biomarkers and adaptive precision clinical trials." (PMID 40959087, 2025). "Given the connection among AT-I, nicotine, miR-21, NLRP3, ROS, PTEN, inflammation, and sepsis, we speculate that AT-I may inhibit nicotine-induced septic damage by regulating miR-21, PTEN, and ROS/NLRP3 pathways, which warrants further experiments for verification in the future." (PMID 40422906, 2025). "Additionally, pharmacological inhibition of the NLRP3-caspase-1 inflammasome has demonstrated a reduction in the expression of both GSDMD and its cleavage form, GSDMD-N, effectively mitigating pyroptosis in the mouse brain following sepsis." (PMID 38627764, 2024). "Peritoneal dynamics seems to be selectively modulated by NLRP3 as evidenced in mouse models of sepsis, where adult mice lacking NLRP3 were protected when induced with polymicrobial sepsis, whereas NLRP3 deficiency did not improve survival in neonatal mice underwent cecal slurry." (PMID 38842647, 2024). "Studies have shown that the activation of the NLR family pyrin domain containing 3 (NLRP3) inflammasome and subsequent pyroptosis in macrophages can lead to the release of proinflammatory factors, such as IL-1β, thereby augmenting inflammatory responses observed in conditions like sepsis." (PMID 38705396, 2024). "Once formed, the NLRP3 inflammasome activates caspase-1, which subsequently mediates the cleavage of pro-IL-1β and pro-IL-18 and the secretion of their bioactive forms, important players in the systemic inflammation and cardiac dysfunction (and MOF) during sepsis." (PMID 39559354, 2024). "This could also be the reason why some prominent pathways that are well known to be activated in sepsis, such as NLRP3 inflammasome pathway, were not significantly altered in our data." (PMID 38343542, 2024). "Interestingly, NLRP3 is an effective indicator of sepsis and septic shock and is no less accurate than the SOFA score." (PMID 38716051, 2024). "In addition, YOD1-mediated coagulation in MRSA-induced sepsis was blocked by the administration of MCC950, a highly potent and specific inhibitor of NLRP3, which supported that YOD1-regulated NLRP3 inflammasome-dependent coagulation in the process of MRSA-induced DIC." (PMID 38789414, 2024). "However, whether HSF1 regulated NLRP3 in sepsis-induced brain injury, as well as the detailed mechanism of HSF1 in brain injury, remains unknown in the sepsis model." (PMID 36741074, 2023).
Sepsis (continued). "NLRP3 inflammasome assembly and activation can self‐cleavage to produce an active form of Caspase‐1 (pro‐Caspase‐1), promoting the release of proinflammatory cytokines including IL‐1β, IL‐18, and the alarmin high mobility group protein B1 (HMGB1), en route to inflammation of sepsis." (PMID 37206244, 2023). "In DEFA1/DEFA3 transgenic mice, increased gene copy numbers of DEFA1/DEFA3 worsen sepsis by inducing endothelial pyroptosis and vascular permeability in a canonical Nod-like receptor family pyrin domain containing 3 (NLRP3)/caspase-1 inflammasome dependent manner." (PMID 35935811, 2022). "Our result showed a considerable decrease in NLRP3, GSDMD-N, IL-18 protein expression, and serum IL-1β levels in the AFC and ASC groups compared to the ANC group, indicating that FMT and SCFAs can suppress cell pyroptosis and have a protective function in sepsis." (PMID 36713461, 2022). "In conclusion, this study found that ceramide-mediated endothelial pyroptosis depends on the activation of ROS-dependent TXNIP/NLRP3/GSDMD signalling, and TXNIP inhibition may provide an important adjuvant therapeutic approach for alleviating vascular endothelial injury in sepsis and other diseases." (PMID 36517743, 2022). "It is tempting to speculate that NLRP3 activation can complement inefficient NAIP/NLRC4 activation in human macrophages under certain conditions, for example in sepsis when LPS levels are high, as our mRNA expression data suggests NLRC4 expression is lowered under these conditions." (PMID 33380493, 2021). "Whether or not deleting Nlrp3 would prevent cardiac atrophy and improve diastolic cardiac function in sepsis was unclear." (PMID 34472725, 2021). "Our results showed a close association between TNF-α production but not IL-1β or IL-6 with the NLRP3 29940 G>C variation in sepsis patients, which might be due to the complex inflammatory system in the host." (PMID 34172780, 2021). "Some treatment options for sepsis-induced ALI have been explored, albeit the unmet need to identify safer and more effective drugs that may target mitochondrial ROS-mediated activation of NLRP3 inflammasome." (PMID 34737695, 2021). "Thus, sepsis still launches acute proinflammatory response in the brain without the participation of NLRP3 or IL-1R1." (PMID 32070376, 2020). "Upregulated autophagy may be insufficient to counteract the NLRP3 inflammasome-induced negative effects of inflammation increases during sepsis." (PMID 33324236, 2020). "NLRP3-immunocompromised septic patients who survived and recovered from sepsis (n = 3) did not have detectable levels of IL-6 in their plasma at 120 days after the septic episode, but their NLRP3 inflammasome could be activated normally." (PMID 31221993, 2019). "In the present study, we assess the activation of NLRP3 inflammasome by the P2X7 receptor in blood leukocytes from a cohort of clinically relevant intra-abdominal origin sepsis patients and then carry out a follow-up analysis of the same individuals after sepsis resolution." (PMID 31221993, 2019). "However, in monocytes from NLRP3 compromised septic patients, P2X7 receptor expression did not correlated with IL-1β release, suggesting an alternative role for P2X7 receptors in sepsis." (PMID 31221993, 2019). "We investigated if absence of Nlrp3 affects muscular cytokine expression in sepsis." (PMID 28097512, 2017). "Therapeutic effects of CORM-2 on sepsis-induced AKI were assessed by measuring serum creatinine (Scr) and blood urea nitrogen (BUN), kidney histology scores, apoptotic cell scores, oxidative stress, levels of cytokines TNF-α and IL-1β, and NLRP3 inflammasome expression." (PMID 26334271, 2015). "None the less, our observations suggest that the NLRP3 inflammasome may be a potential therapeutic target for the treatment of sepsis-induced myocardial dysfunction." (PMID 25216263, 2014).
Sepsis (continued). "Consequently, the activation of the NLRP3 inflammasome may be significant for the upkeep of the intestinal epithelial barrier in ALD patients, preventing bacterial translocation in the gut postinfection, and improving the prognosis of sepsis patients." (PMID 39605303, 2024). "However, it still not clear whether SKP2 is involved in the process of NLRP3 ubiquitination and what is the underlying mechanism for the alteration of SKP2 activity in sepsis-induced lung injury." (PMID 38698431, 2024). "It is not clear whether HSPA8 mediates lung injury by regulating NLRP3 inflammasome in sepsis." (PMID 38698431, 2024). "In addition, the sepsis-induced systemic inflammation (measured as an increase in inflammatory cytokines and chemokines in the serum) and the cardiac activation of NF-kB (IKK) and the NLRP3 inflammasome were significantly reduced in CLP-mice treated with PRT062607." (PMID 39559354, 2024). "Finally, whether or not deletion of Nlrp3 attenuates cardiac atrophy in sepsis has not been investigated." (PMID 34472725, 2021). "Moreover, Nlrp3-KO mice, submitted to polymicrobial sepsis induced by cecal ligation and puncture surgery, had a survival benefit and did not lose body or muscle weight during 96 h of sepsis, when compared to wild type ones." (PMID 34831246, 2021). "Baicalin could significantly reduce IL-1β in the sera of bacterial infected mice and could inhibit NLRP3 inflammasome activation through augmenting PKA signaling, thereby improving mouse survival in bacterial sepsis and could reduce the level of LPS, TNF-α, and IL-6 in the blood of sepsis mice." (PMID 34938184, 2021). "Firstly, we found that CD14+ monocytes from pneumonia-induced sepsis patients had considerably greater levels of the proteins TLR4, NLRP3, ASC1, cleaved caspase-1, IL-1, and GSDMD in contrast to pneumonia patients without sepsis and healthy people." (PMID 36923408, 2023). "Another inhibitor of NLRP3 inflammasome activation identified in platelets is Ibrutinib, an inhibitor of Bruton’s tyrosine kinase (BTK), but its potential efficacy in sepsis has not yet been established." (PMID 37108623, 2023). "The results showed that after treatment in 75 sepsis patients with ARDS (SARDS) and 75 sepsis patients without ARDS (SNARDS), the concentration of NLRP3 in serum was significantly reduced." (PMID 37649483, 2023). "We first compared the differences in serum NLRP3 concentrations in 75 sepsis patients with ARDS (SARDS), 75 sepsis patients without ARDS (SNARDS), and 60 age-matched healthy controls." (PMID 37649483, 2023). "Among them, the NLR family pyrin domain containing 3 (NLRP3) inflammasome is best characterized and shows sustained activation in sepsis through canonical CASP1-dependent or non-canonical CASP4/5/11-mediated pathway." (PMID 33776776, 2021). "Murine models of sepsis-induced ALI mimic TLR3, TLR4, TLR7 and NLRP3 activation but, unlike the human disease, also activate TLR2 and TLR9." (PMID 33672738, 2021). "In sepsis-induced AKI models, PKM2 inhibition attenuates the activation of NLR family pyrin domain containing 3 (NLRP3) and absent in melanoma 2 (AIM2) inflammasomes, decreases the release of IL-1β, IL-18, and HMGB1 by macrophages, and ultimately improves survival outcomes." (PMID 40843128, 2025). "In sum, all that can be said in general about innate activation in sepsis is that TLR2, TLR4, TLR5, TLR7 and NLRP3 can be, but are not necessarily, activated, while TLR9 may or may not be downregulated." (PMID 33672738, 2021). "In addition, similar trends were found in organ injury and dysfunction, in which sepsis-induced lung injury and impaired function of the liver and the kidney were attenuated under the administration of PHZ-OH rather than by deleting NLRP3." (PMID 35982051, 2022).